DCC (DCC netrin 1 receptor)
Diseases named in the same sentence as DCC in open-access papers (continued):
Sharing a sentence is not in itself a finding about the gene and the disease.
colorectal cancer (continued). "It is now well-established that netrin-1 elicits chemoattractant guidance by binding to its canonical receptors deleted in colorectal cancer (DCC) and neogenin, or chemorepellant guidance by binding to the DCC/uncoordinated (Unc5) A–D receptor complex." (PMID 29017609, 2017). "Instead of binding to Slit1-3, mammalian Robo3 forms a protein complex with the Netrin-1 receptor DCC (Deleted in Colorectal Cancer) through their cytoplasmic domain." (PMID 28234971, 2017). "The interaction between the secreted ligand Netrin-1 and its receptor Deleted in Colorectal Carcinoma (DCC) is thought to control midline attraction of crossing axons." (PMID 28240285, 2017). "We show that ESCRT-II is present in RGC axonal growth cones (GCs) where it co-localizes with endocytic vesicle GTPases and, unexpectedly, with the Netrin-1 receptor, deleted in colorectal cancer (DCC)." (PMID 27248654, 2016). "We develop a system for the light-dependent activation of a guidance receptor, Deleted in Colorectal Cancer (DCC), using Arabidopsis thaliana Cryptochrome 2, which oligomerizes upon blue-light absorption." (PMID 27052670, 2016). "The netrin receptor deleted in colorectal cancer (DCC) is a potential receptor for NTN5 in MNs, as similar ectopic neurons were found in Dcc mutant mice, but not in mice deficient for other netrin receptors." (PMID 26858598, 2016). "The guidance receptors deleted in colorectal cancer (DCC) and neuropilin, for example, are rapidly endocytosed upon binding Netrin-1 and Sema3A, respectively." (PMID 27248654, 2016). "The ligand-receptor pair, Netrin (Net) and Frazzled (Fra) (DCC, Deleted in Colorectal Cancer, in vertebrates), is recognized as the prototypical effector of chemoattraction, with roles in both long- and short-range guidance." (PMID 27743477, 2016). "Expression of netrin receptors, Unc5H2 (Unc-5 homolog B, C. elegans) and DCC (deleted in colorectal carcinoma), was found in Müller cells and astrocytes." (PMID 26732856, 2016). "The netrin-1 receptor, DCC, was discovered as a putative tumor suppressor gene in colorectal cancer." (PMID 26207151, 2015). "DCC is located on chromosome 18q, which is the most common deleted chromosomal region in colorectal cancer as well as gastric cancer." (PMID 26207151, 2015). "The cellular response to Netrins is dictated by its receptors: deleted in colorectal cancer (DCC) and perhaps Neogenin enable attraction to Netrin-1, while Unc5 proteins, in some cases in conjunction with DCC, elicit repulsion from Netrin-1." (PMID 26633881, 2015). "DCC (netrin-1), originally discover in colorectal cancer, is characterized as a candidate tumor suppressor gene that encodes the netrin 1 receptor, a member of the immunoglobulin superfamily of cell adhesion molecules." (PMID 26602921, 2015). "Deleted in colorectal cancer (DCC), a netrin-1 receptor (PDB ID: 3lafA), was selected as a different template (lower sequence identity, 25.51%; QMEAN Z-score, -3.23) in molecular modeling of the longer, 1-252aa segment of nmMLCK1." (PMID 26111161, 2015). "Two genes correspond to more than two of the 139 CpGs, both are well-known tumour suppressor genes: DCC (DCC = Deleted in Colorectal Cancer) and GATA4." (PMID 24934728, 2014). "The expression of the deleted in colorectal cancer (DCC) gene is frequently lost in intestinal cancers." (PMID 24963031, 2014). "Degradation of RIP-generated intracellular domain fragments has been reported for other γ-secretase substrates such as Notch, syndecan-3, nectin-1α, p75, deleted in colorectal cancer (DCC) and members of the APP family." (PMID 24015300, 2013).
colorectal cancer (continued). "Protogenin (PRTG) belongs to the immunoglobulin superfamily and is most closely related to the deleted in colorectal cancer (DCC)-Neogenin subclass, which, in addition to DCC and Neogenin, includes Punc and Nope." (PMID 24007463, 2013). "Chromosome 18q21.1 harbours the tumour suppressor genes SMAD4, SMAD2 and deleted in colorectal cancer (DCC) genes." (PMID 23110075, 2012). "Utilizing this approach, we reveal a new role for the secreted UNC-6/Netrin ligand and its transmembrane receptor UNC-40/Deleted in colorectal cancer (DCC) in SPR." (PMID 21663630, 2011). "Whereas DCC (Deleted in colorectal cancer) alone can mediate Netrin-dependent attraction, Unc5a can function alone or with DCC to mediate repulsion." (PMID 20569485, 2010). "The guidance cue netrin-1 organizes neuronal networks by attracting or repelling cellular processes through DCC (deleted in colorectal cancer) and UNC-5 homologue (UNC5H) receptors, respectively." (PMID 20628609, 2010). "Another gene, DCC (deleted in colorectal cancer), is found to be in close proximity to SMAD4 in the human 18q21.1-q21.2 region." (PMID 20707908, 2010). "Two distinct families of netrin-1 receptors, the DCC (deleted in colorectal cancer) and UNC-5 homologue families (UNC5H; A-D), account for the bifunctional nature of netrin-1." (PMID 20628609, 2010). "Deleted in colorectal cancer (DCC) is a marker expressed selectively on callosal axons arising from neurons within the cingulate cortex." (PMID 19961580, 2009). "The nominally significant intragenic SNPs were found in several genes, including cadherin 9 type 2 (CDH9) on 5p14 and gene deleted in colorectal carcinoma (DCC) on 18q21." (PMID 17903296, 2007). "More than half of these were in or near several genes, including cadherin 9 type 2 (CDH9) on 5p14, nuclear receptor subfamily 5, group A gene (NR5A2) at 1q32, gene deleted in colorectal carcinoma (DCC) on 18q21, and PPARG on 3p25." (PMID 17903296, 2007). "This negative regulation of ephrin-B signaling mediated by γ-secretase activity is very similar to what has been recently reported for deleted in colorectal cancer (DCC) in synaptic function." (PMID 16930449, 2006). "The DCC (deleted in colorectal carcinoma), proximal to MBD2, is the largest gene in this region, but no statements about its expression can be made because of a lack of informative expression measures." (PMID 16982006, 2006). "In more than 90% of primary colorectal cancers with LOH of chromosome 18q, DCC is included in the region of allelic loss." (PMID 15956977, 2005). "Using a bacterial fusion protein, a deleted colorectal carcinoma (DCC)-specific monoclonal antibody (MAb) 127-22 was established." (PMID 9472645, 1998). "In addition, the expression levels of neuropilin 1 and neuropilin 2, receptors for Sema3A, and Neogenin and deleted in colorectal cancer (DCC), receptors for Netrin-1, were evaluated by RT-qPCR." (PMID 36986209, 2023). "During development, multiple guidance cues can control the guidance of axons to their specific targets and help establish functional neural circuits, such as netrin‐1 (NTN‐1)/deleted in colorectal carcinoma (DCC), Slit3/robo, Semaphorin5A/plexin, and ephtinB/ephB pathways." (PMID 36852451, 2023). "Netrin-1 could bind to the receptors deleted in colorectal cancer (DCC), neogenin-1(Neo-1), or uncoordinated (UNC5) and then participate in the formation of various chronic pain conditions." (PMID 35966013, 2022). "This study was based on the notion that the interaction of netrin-1 with its receptor deleted in colorectal carcinoma (DCC) might involve an additional co-receptor, since netrin-1 protein only co-immunoprecipitate with DCC if cross-linked." (PMID 35910389, 2022).
colorectal cancer (continued). "Supporting this, FEZ1 colocalizes with VAMP2 in developing hippocampal neurons and forms a separate complex with deleted in colorectal cancer (DCC) and Syntaxin-1 (Stx1), components of the Netrin-1 signaling pathway that are also involved in regulating axon and dendrite development." (PMID 33771901, 2021). "Besides, Presenilin1 also cleaves another type 1 transmembrane protein such as Alcadein α, Deleted in colorectal cancer (DCC), LDL receptor family (LRP1 and LRP8), p75-neurotrophin receptor (p75NTR), NOTCH receptor." (PMID 34781973, 2021). "Chemoattractive signaling effected, for instance, via Netrin-1 through its receptors deleted in colorectal cancer (DCC) and Down’s syndrome cell adhesion molecule (DSCAM), is responsible for the attraction of commissural axons toward the midline in the spinal cord." (PMID 33771901, 2021). "In addition, DSCAM and deleted in colorectal carcinomas (DCC) are both receptors of netrin-1, which serves as an important axon guidance cue during neural development." (PMID 34136475, 2021). "Such functions may be conserved, since the drosophila homolog still life/Tiam1 and C. elegans TIAM-1/GEF function during synaptic and, axonal patterning downstream of the netrin receptor UNC-40/DCC (Deleted in Colorectal Cancer), respectively." (PMID 30694177, 2019). "As one of genetic marker for diagnosis of colorectal cancer, DCC could inhibit the growth of colorectal cancer." (PMID 30792708, 2019). "The expression of DCC protein was up-regulated after T. gondii infection, which suggested that T. gondii infection might improve the resistance of host against colorectal cancer through increasing the expression of DCC protein." (PMID 30792708, 2019). "Indeed, our own studies have shown that Netrin-1/Deleted in Colorectal Cancer (DCC) signaling triggers exocytosis through the SNARE Syntaxin-1 (STX1)." (PMID 29912942, 2018). "Knockdown of BCL11A-L, downregulates expression of MAP1B and the axon-guidance receptor DCC (deleted in colorectal cancer), and induces axon branching, multi-axon formation, and dendrite outgrowth with suggestions that BCL11A-L plays an important role in neural circuit formation during development." (PMID 30150678, 2018). "DCC was initially discovered as a tumor suppressor associated with an allelic deletion of chromosome 18 in human colorectal cancer but later experimental studies have demonstrated that DCC mediates the chemoattractive guidance effect of Netrin-1 on rat spinal commissural axons." (PMID 28245592, 2017). "To characterize the signaling mechanism underlying netrin-1’s effects on vascular function, we assessed levels of its receptor ‘deleted in colorectal cancer’ (DCC) and components of its downstream pathway in aortic tissues from non-diabetic and diabetic WT and Tg3 mice." (PMID 29059224, 2017). "We found that draxin-induced growth cone collapse critically depends on draxin receptors (deleted in colorectal cancer, DCC), inhibition of protein kinase B/Akt, activation of GSK-3β (glycogen synthase kinase-3β) and the presence of microtubule-associated protein MAP1B." (PMID 25775433, 2015). "The DCC (deleted in colorectal cancer) family includes the DCC and neogenin receptors." (PMID 25143950, 2014). "The growth and guidance of many axons in the developing nervous system require Netrin-mediated activation of Deleted in Colorectal Cancer (DCC) and other still unknown signaling cues." (PMID 24400119, 2014).
colorectal cancer (continued). "In Caenorhabditis elegans, the guidance receptor UNC-40 (DCC, deleted in colorectal cancer) is localized to the ventral side of the hermaphrodite specific neurons (HSN) before they extend axons ventrally towards the ventral nerve cord, where the UNC-6 (netrin) guidance cue is secreted." (PMID 22606267, 2012). "In a study of 57 colorectal cancers, it was found that there were almost never any mutations in the DCC gene in human colorectal tumours showing 18q allelic loss." (PMID 19424478, 2008). "We have noted an effect of the cytokines on expression for genes for two proteins first described in cancer biology, rat homologs for breast cancer 1 (BCR1), called BCRA1, and deleted in colorectal cancer (DCC), both of which have subsequently been reported to be present in neurons." (PMID 18088439, 2007). "LOH at 18q indicates presence of several TSGs including Deleted in Colorectal Carcinoma (DCC), SMAD2, and SMAD4; loss of expression of 18q LOH plays a significant role in CRC pathogenesis." (PMID 33374459, 2020). "As netrin-1 and its receptor deleted in colorectal cancer (DCC) are important regulators in neuronal and vascular activities, the present study attempted to explore whether netrin-1 and DCC are involved in the neuroprotection of stem cell-based therapies in a rat ischemic stroke model." (PMID 29017609, 2017). "Finally, APPL1 may also act as a proapoptotic factor by interacting with DCC (deleted in colorectal cancer) and enhancing the DCC‐induced apoptosis in colorectal cancer cells." (PMID 22989406, 2013). "There are at least three means to achieve this survival advantage: loss of netrin-1 receptors expression, as extensively described in human colorectal cancer for DCC or/and UNC5H; loss of downstream death signalling induced by DCC or UNC5H; or gain of autocrine or paracrine expression of the ligand." (PMID 24293316, 2013). "Back in the early 1990s, Vogelstein and colleagues suggested that a gene called DCC (for Deleted in Colorectal Cancer) could be a tumour suppressor gene because it was found to be deleted in more than 70% of colorectal cancers, as well as in many other cancers." (PMID 15956977, 2005). "In addition, deleted in colorectal cancer (DCC), instead of neogenin-1(Neo-1) or uncoordinated (UNC5), was proved to be the specific functional receptor of Netrin-1 in regulating visceral hypersensitivity, whose upregulation may result in the most severe symptoms in the prepubertal period." (PMID 35966013, 2022). "Results of APC and DCC LOH, KRAS and microsatellite instability indicate our colorectal cancer cases were typical of sporadic cancers following the ‘chromosomal instability’ pathway." (PMID 26970738, 2016). "Movement toward UNC-6/Netrin can be mediated, in part, by the receptor UNC-40, a homolog of DCC (Deleted in Colorectal Cancer), and movement away from UNC-6/Netrin can be mediated by the receptor UNC-5 acting with UNC-40/DCC." (PMID 27035721, 2016). "As an additional technical validation step, we assayed four genes (APC, MACC1, DCC, and DSC2) that have been previously established to be differentially expressed between tumor and adjacent normal tissue in colorectal cancer." (PMID 22363440, 2012). "DCC (Deleted in Colorectal Carcinoma) is an important tumour suppressor gene, whose expression is significantly reduced or absent in most advanced colorectal cancers and many other cancers." (PMID 40260608, 2025). "TrkC-KF-Gal4DBD is unable to transactivate the UAS-GAL4, unlike deleted in colorectal cancer intracellular domain (DCC-IC)." (PMID 29750782, 2018).
colorectal cancer (continued). "For example, the lead SNP within the associated region on chromosome 18 lies in intron 9 of the DCC netrin 1 receptor (originally named deleted in colorectal cancer; DCC) gene, with no other protein-coding genes for >500 kb on either side." (PMID 29187730, 2017). "DCC is a RAF kinase inhibitory protein (RKIF), previously called phosphtidylethanolamine binding protein, which seems to have tumor suppressor activity and is deleted in several types of tumors, including some colorectal cancers in humans." (PMID 18088439, 2007). "For example, introduction of an intact copy of chromosome 18 into a colorectal cancer cell line lacking endogenous DCC expression yielded detectable levels of DCC transcripts and resulted in suppression of growth in soft agar and tumorigenicity in nude mice." (PMID 15956977, 2005). "In addition, one gene, DCC (deleted in colorectal carcinoma), which was not differentially expressed in the previous study, was significantly decreased in CHD8+/− organoids." (PMID 28321286, 2017). "Moreover, deletions of 18q, 8p, 4p and 15q, inactivation of SMAD4, DCC is considered as discussible factor of negative prognosis of colorectal cancer and other tumors." (PMID 27276710, 2016). "Therefore, we did not investigate other factors affecting prognosis, such as microsatellite instability (MSI), CRC patients with ulcerative colitis (UC), the impact of anastomotic leakage after surgery on colorectal cancer (CRC), the chromosome 18q genotype, DCC status, etc." (PMID 26030771, 2015). "The guidance receptor DCC (deleted in colorectal cancer) ortholog UNC-40 regulates neuronal asymmetry development in Caenorhabditis elegans, but it is not known whether DCC plays a role in the specification of neuronal polarity in vertebrates." (PMID 22606267, 2012).